CDCA7 (cell division cycle associated 7)
Diseases named in the same sentence as CDCA7 in open-access papers (continued):
Sharing a sentence is not in itself a finding about the gene and the disease.
peripheral T cell lymphoma (1 paper, 2019). "In an L-HES patient who progressed to peripheral T cell lymphoma, the malignant transformation identified increases in the expression of CDCA7, TIGIT, and TOX, which are highly expressed in SS, suggesting that these genes contribute to neoplastic transformation." (PMID 31489115, 2019).
Sepsis (1 paper, 2025). Sepsis is defined as life-threatening organ dysfunction caused by a dysregulated host response to infection. "Ultimately, 8 key genes were identified: CD160, HELB, ING4, PIP5K1C, SRPRA (HR < 1); and CDCA7, FAM3A, PPP1R15A (HR > 1), and the hub genes showed apparent differences in expression between alive and dead sepsis patients." (PMID 40612938, 2025). "A lactylation-based prognostic model was developed, comprising eight key genes (CD160, HELB, ING4, PIP5K1C, SRPRA, CDCA7, FAM3A, PPP1R15A), and demonstrated strong predictive performance for sepsis outcomes (AUC = 0.78 in the training cohort; AUC = 0.73 in the validation cohort)." (PMID 40612938, 2025).
Shock (1 paper, 2022). The state in which profound and widespread reduction of effective tissue perfusion leads first to reversible, and then if prolonged, to irreversible cellular injury. "We also found that, the two hub genes, ASB13 and CDCA7, were both apoptosis-related genes, suggesting that ECMO may affect the prognosis of patients through apoptosis, in the AMI complicated by cardiogenic shock." (PMID 36531699, 2022).
Stroke (1 paper, 2022). Sudden impairment of blood flow to a part of the brain due to occlusion or rupture of an artery to the brain. "Exclusion of women younger than 50 years of age at stroke diagnosis attenuatedIVW estimates (ORIVW = 0.95, 95% CI: 0.70–1.27) and effect estimates forthe SNPs in the AMH, CDCA7 and TEX41 loci." (PMID 39076620, 2022).
uterine endometrioid carcinoma (1 paper, 2020). "In uterine endometrioid carcinoma, the prevalent high mRNA expression of almost all CDCAs except CDCA7, the amplification of NUF2, CDCA3/5, the deep deletion of CDCA2 and the missense mutation of CDCA7 presented the most common altered genetic events." (PMID 32913454, 2020).
tumor (28 papers, 2011 to 2026). "As for immunity, CDCA7 was remarkably associated with immune infiltration, tumor microenvironment, immune checkpoint molecules and immune pathways." (PMID 33648519, 2021). "The association of CDCA7 with these tumor-related immunosuppressive molecules suggested its important potential functions in human immunity." (PMID 33648519, 2021). "Numerous studies verify that CDCA7 is highly expressed in a variety of malignancies and closely associated with tumor progression, invasion and metastasis." (PMID 34551671, 2021). "CDCA7 is closely associated with cell cycle regulation in tumor cells." (PMID 40630134, 2025). "Due to the close relationship between CDCA7 and cell cycle in tumor cells, we explore the impact of circASH1L-mediated regulation of CDCA7 on cell cycle progression." (PMID 40630134, 2025). "CDCA7 overexpression promoted tumor growth, whereas CDCA7 knockdown inhibited tumor growth, as evidenced by tumor volume and weight." (PMID 39905019, 2025). "Other genes, such as the cell division cycle-associated protein (CDCA) 1-8 family, are thought to be involved in tumor progression, with high expression levels of CDCA7 correlating with shorter disease-free survival in patients with GC." (PMID 39941831, 2025). "Consistent with the in vitro results, in vivo experiments showed CDCA7 overexpression promoted tumor resistance to gemcitabine, a phenomenon that is reversed following 2-DG treatment." (PMID 39905019, 2025). "CDCA7 is a DNA-binding protein that acts as a transcriptional regulator that mediates tumor promotion and is involved in cell division." (PMID 40732340, 2025). "CDCA7 overexpression has been correlated with advanced clinical features, tumor development, and metastatic relapse." (PMID 40732340, 2025). "CDCA7 has been consistently reported in many research studies to play a remarkable role in tumor progression in various types of cancers." (PMID 39703843, 2024). "Compared with the tissues and control cell lines, the CDCA7 protein was up-regulated in human tumor biopsy specimens and Burkitt lymphoma cell lines, respectively." (PMID 38333875, 2024). "Future studies are warranted to validate the effects of CDCA7 on tumor biology and macrophage polarization in biological experiments such as cell culture and mouse models." (PMID 36860864, 2023). "The correlation of CDCA7 to ferroptosis and tumor infiltration of 22 kinds of human immune cells and the association between CDCA7 and immune checkpoint molecules were analyzed." (PMID 37510310, 2023). "Consistently, in comparison with adjacent normal tissues, CDCA7 protein and mRNA levels were significantly upregulated in tumor tissues of OC patients." (PMID 34551671, 2021). "The tumor growth rate of the KYSE150 group was significantly faster than that of the CDCA7-knockdown group." (PMID 34737951, 2021). "Immunohistochemistry was further used to detect the tumor tissue stripped from nude mice with anti-CDCA7, anti-CCNA2, and anti-Ki-67 antibodies." (PMID 34737951, 2021). "Quantification analysis of CDCA7 levels in tumor tissues and adjacent normal tissues of OC patients was done in GEPIA database." (PMID 34551671, 2021). "Meanwhile, CDCA7 as a DNA-binding protein can function as a transcription regulator to mediate the tumor-promoting effect." (PMID 34737951, 2021). "To confirm the oncogenic role of CDCA7 in vivo, we established a subcutaneous transplantation tumor model in female NU-Foxn1nu nude mice using stable CDCA7-knockdown KYSE150 and KYSE150 cells." (PMID 34737951, 2021). "The mean tumor weight of the control group and the CDCA7-knockdown group was 209.61 ± 108.84 and 54.23 ± 19.39 mg, respectively (t-test, P < 0.001)." (PMID 34737951, 2021). "The AUC of the CDCA7 expression was 0.660, higher than that of age, gender, race and lymph nodes status, and lower than that of tumor grade, pathological stage, T stage and M stage." (PMID 33648519, 2021).
tumor (continued). "As to the tumor microenvironment, CDCA7 was shown to be involved in immune cells, stromal cells and both of them (P < 0.001)." (PMID 33648519, 2021). "Here, we analyzed the copy number amplification data from TCGA through cBioPortal and found that the copy number amplification of CDCA7 existed in various kinds of tumor." (PMID 34737951, 2021). "The results found that the mean tumor volume of the CDCA7-knockdown group and the control group was 158.74 ± 24.83 and 488.41 ± 35.84 mm3, respectively (t-test, P < 0.001)." (PMID 34737951, 2021). "Due to loss of biopsy cores, insufficient tumor cells present in the cores or affluence of necrotic tissue, 72/80 FFPE specimens were evaluated for CCNB2, KIAA0101, SLC27A2, ASPM, and CDCA7 immunostaining." (PMID 23282137, 2013). "CDCA7 gene encodes 371 amino acid proteins, which are abnormally expressed in various tumor tissues." (PMID 38333875, 2024). "We then conducted a prognostic analysis of CDCA7 and found that CDCA7 was a risk factor, CDCA7 gene encodes 371 amino acid proteins, which are abnormally expressed in various tumor tissues." (PMID 38333875, 2024). "The expression of CDCA7 was significantly correlated with tumor-infiltrating immune cells." (PMID 37510310, 2023). "Moreover, the target gene of Myc CDCA7 is reportedly overexpressed in human cancer and promotes tumor transformation." (PMID 36860864, 2023). "As a responsive gene of c-MYC and E2F1, CDCA7 participates in tumor transformation." (PMID 37510310, 2023). "In addition, we found that CDCA7 level has a strong correlation with tumor-infiltrating immune cells and immune checkpoint molecules, revealing its potential function in regulating the prominent biological processes in tumor progression." (PMID 37510310, 2023). "Interestingly, CDCA7 is a DNA-binding protein and regulates the gene expression of the tumour-promoting effect of c-Myc and E2F1." (PMID 35167614, 2022). "CDCA7 expression was elevated in tumor tissues of OC patients and OC cell lines." (PMID 34551671, 2021). "Furthermore, CDCA7 levels in five pairs of clinical tumor tissue specimens and adjacent normal ones were assessed by performing IHC, western blot and RT-qPCR assay." (PMID 34551671, 2021). "In our previous WGS analysis of 31 ESCC tumor tissues and matched adjacent non-tumor tissues, we identified some genes with copy number variation, including cell division cycle-associated 7 gene (CDCA7), that was amplified in 5 out of 31 ESCC patients." (PMID 34737951, 2021). "Furthermore, we verified that CDCA7 has as a tumor-promoting role in ESCC, and elaborated on its potential mechanisms of carcinogenesis." (PMID 34737951, 2021). "A relatively higher level of CDCA7 was observed in tumor tissues of OC patients." (PMID 34551671, 2021). "Moreover, CDCA7 was significantly correlated with tumor-related immunosuppressive molecules including PDCD1, CD274, CTLA4, BTLA and LAG3." (PMID 33648519, 2021). "The influence of CDCA7 on tumor metastasis has gradually attracted the attention of researchers." (PMID 34551671, 2021). "Our results reveal a novel mechanism of CDCA7 that it may act as an oncogene by directly upregulating CCNA2 to facilitate tumor progression in ESCC." (PMID 34737951, 2021). "Thus, the role of CDCA7 in ferroptosis may be dependent on its tumor microenvironment, which integrates various regulatory factors and thus determines the fate of the cells." (PMID 37510310, 2023). "The results indicated that CDCA7 gene might act as a tumor promoter in ESCC and its copy number amplification or increased expression may accelerate the cell cycle process and promote cell proliferation by binding to the genome of CCNA2 functional domain and increasing its expression in ESCC." (PMID 34737951, 2021).
tumor (continued). "Of ten genes replicated in the HEXA Study dataset, three tumor suppressor genes, CDCA7, KIAA1432, and CCDC67, which were functionally annotated with Polyphen-2 may directly or indirectly play key roles in the development of PTB through immune system and inflammatory responses." (PMID 28355295, 2017). "Across CDCA2, CDCA3, CDCA4, CDCA5, CDCA7, and CDCA8, we observed significantly lower promoter methylation levels in primary tumor samples compared to normal samples, suggesting hypomethylation of these genes in GBM tumors." (PMID 40114265, 2025). "Western blot analysis showed that sh-circASH1L accelerated the cisplatin-induced reduction of GPX4 and SLC7A11 expression, as well as the downregulation of CDCA7 and RRM2 in tumor tissues." (PMID 40630134, 2025). "Interestingly, we found that CDCA7 exhibited a negative association with tumor prognosis." (PMID 36860864, 2023). "CDCA7, CELSR3, PACS1, SNTB1, and TBC1D31 showed consistent upregulation in CRC tumor samples and pre-surgical cfRNA, while GFI1B, HPGD, SH3BGRL2, SIAE, PKHD1L1, and TDP2 showed downregulation in CRC tumor samples and pre-surgical cfRNA." (PMID 37091184, 2023). "In this study, we uncovered the potential prognostic value of CDCA7, one of the copy number altered genes, for ESCC patients; revealed the tumor-promoting role of CDCA7 gene; and explored its possible mechanism in ESCC for the first time." (PMID 34737951, 2021). "Additionally, IHC showed that CDCA7 level was positively correlated with the expression of the proliferation indicators Ki-67 and PCNA in subcutaneous tumor tissues derived from mice." (PMID 39905019, 2025). "Additionally, the analysis of the CGGA and TCGA databases also showed that CDCA7 was closely related to several tumor-related suppressors, including CD80, CD276, CD28, PDCD1LG2, and TNFSF4, which contribute to tumor development via multiple mechanisms." (PMID 37510310, 2023). "IHC staining confirmed the high expression of CDCA7 in tumor tissues compared to the adjacent non-tumor tissues." (PMID 34551671, 2021). "In summary, our study shows that CDCA7, a copy number amplification gene in ESCC, may act as a tumor promoter via regulating CCNA2 directly and accelerate the cell cycle process of ESCC cells." (PMID 34737951, 2021). "In this study, we noticed that CDCA7 was remarkably elevated in the collected tumor tissues of OC patients and OC cell lines compared to the normal ones." (PMID 34551671, 2021). "Meanwhile, CDCA1–5 and CDCA8 demonstrated the weak correlations in the tumor purity, whereas the associations of CDCA6 and CDCA7 were weak and negative." (PMID 33665158, 2020). "The CDCA7, and KIAA0101 may therefore only have role in tumor initiation." (PMID 23282137, 2013).
cancer (21 papers, 2007 to 2025). A tumor composed of atypical neoplastic, often pleomorphic cells that invade other tissues. "Among these, cell division cycle associated 7 (CDCA7) attracted our attention due to its emerging role in the cell cycle and ferroptosis regulation in cancer cells." (PMID 40630134, 2025). "CDCA7 has been previously reported to play a significant role in cancer progression in diverse types of malignancies." (PMID 39703843, 2024). "Similar to MYC, which is often over-expressed in human cancer, CDCA7 is also over-expressed in several human cancers." (PMID 37510310, 2023). "The pairwise boxplot of 72 pairs of ccRCC tissues and matched adjacent normal tissues from TCGA showed most of the cancer tissues exhibited a higher level of CDCA7 (P < 0.001)." (PMID 33648519, 2021). "The expression level of CDCA7 in various cancer cell lines was ten-fold greater to control sample with a high copy number." (PMID 29467944, 2018). "Given the roles of MYC and E2F1 in regulating the production of CDCA7, it is reasonable to assume that CDCA7 may similarly prevent the ferroptosis of cancer cells." (PMID 37510310, 2023). "CDCA7 expression in various cancer cell lines were assessed in CCLE database." (PMID 34551671, 2021). "Subsequently, the expressions of CDCA2, CDCA3, CDCA4, CDCA5, CDCA7, and CDCA8 genes in COAD samples across various cancer stages were verified using the GEPIA2 database." (PMID 39924497, 2025). "Among them, seven genes of CDCAs (CDCA1/NUF2: P = 2.73E-22, CDCA2: P = 1.52E-16, CDCA3: p = 1.50E-20, CDCA5: P = 1.77E-20, CDCA6/CBX2: P = 6.87E-19, CDCA7: P = 5.92E-16, and CDCA8: P = 1.67E-18) were all up-regulated in 19 cancer datasets." (PMID 33665158, 2020). "Many other cancer-related genes showed up differentially expressed in PDAC, including MUC2, MUC5B, MUC13, ALDH3A1, CDCA7, and CCL2." (PMID 31379917, 2019). "Additionally, the data suggest potential new therapeutic targets, such as TOP2A, CDCA7, and STAT1, for future investigations against this aggressive form of cancer." (PMID 40732340, 2025). "Studies have also demonstrated a connection between CDCA7 and c-MYC, a potent cancer oncogene." (PMID 39703843, 2024). "In this regard, CDCA7 may work as a regulator, downstream of MYC, and suppress the ferroptosis of cancer cells." (PMID 37510310, 2023). "CDCA7 expression in OC tissues and adjacent normal tissues was obtained from Gene Expression Profiling Interactive Analysis (GEPIA) and in various cancer cell lines was obtained from Cancer Cell Line Encyclopedia (CCLE)." (PMID 34551671, 2021). "It is known that deregulation of cell cycle control is a fundamental feature of cancer pathogenesis, therefore it was not unexpected that CDCA7 protein has been observed to be expressed at high levels in almost all selected tumors." (PMID 23282137, 2013). "CDCA7 is a downstream target of MYC and is frequently overexpressed in human cancers." (PMID 18059402, 2007). "Additionally, the absence of significant differences in the mRNA expression levels of CDCA2, CDCA3, CDCA4, CDCA5, CDCA7, and CDCA8 across different cancer stages of COAD suggests that these genes may play a consistent role throughout the progression of COAD." (PMID 39924497, 2025).
infection (1 paper, 2021). The state of being infected such as from the introduction of a foreign agent such as serum, vaccine, antigenic substance or organism. "Numerous CDC genes are differentially expressed in the lung tissue of mice recovering from an acute PVM infection, including Cdc20, Cdc20b, Cdca3, Cdca4, and Cdca7." (PMID 34959580, 2021).
CDCA7 also shares sentences with these, for which no sentence is quoted: hepatocellular carcinoma (3 papers); Neurodevelopmental delay (2); adenocarcinoma (1); Alzheimer disease (1); clear cell renal cell carcinoma (1); Combined immunodeficiencies (1); endometrioid adenocarcinoma (1); Ewing sarcoma (1); Exotropia (1); Fanconi anemia (1); gastric adenocarcinoma (1); gastric cancer (1); genetic disorder (1); hematologic cancers (1); hepatoblastoma (1); kidney carcinoma (1); lung squamous cell carcinoma (1); melanoma (1); pancreatic diseases (1); primary immunodeficiency (1); prostate carcinoma (1); small cell lung carcinoma (1); triple-negative breast carcinoma (1); uterus cancer (1); viral infection (1).